CRP (C-reactive protein)
Diseases named in the same sentence as CRP in open-access papers (continued):
Sharing a sentence is not in itself a finding about the gene and the disease.
atherosclerosis (continued). "Experimental studies demonstrated that CRP is detectable in the vascular intima of atherosclerotic lesions where drives all stages of atherosclerosis." (PMID 31110500, 2019). "Further investigation revealed that recombinant CRP per se can already stimulate the proliferation of VSM to promote the onset of atherosclerosis, and this increase in proliferation is found to be mediated through the activation of NF-κB." (PMID 31391207, 2019). "C-Reactive protein (CRP), an acute-phase protein, is an important risk factor for atherosclerosis and coronary heart disease." (PMID 31748592, 2019). "Using a similar study design, associations between an established biomarker of inflammation, serum C-reactive protein levels (CRP) and carotid intima-media thickness (CIMT), a marker of atherosclerosis, were associated with incidence of ischemic stroke." (PMID 31127075, 2019). "Earlier reports have suggested that inflammation plays a key role in atherosclerosis and confirmed that patients with elevated CRP and lower albumin levels have high occurrence rates of PAD." (PMID 31349820, 2019). "When ApoB100/100LDLr−/− mice were employed, which are rich in LDL and develop human-like hypercholesterolemia, CRP slowed the development of atherosclerosis, suggesting an atheroprotective role of CRP." (PMID 31379851, 2019). "Human CRP, mouse CRP and rabbit CRP have all been used to determine the effects of CRP on the development of atherosclerosis." (PMID 31379851, 2019). "In another study employing ApoE−/− mice, CRP promoted early changes of atherosclerosis by directly increasing the transcytosis of LDL across endothelial cells and increasing LDL retention in vascular walls." (PMID 31379851, 2019). "Previous studies have identified several cytokines like interleukin-6 and C-reactive protein (CRP) as potential biomarkers for atherosclerosis, myocardial infarction, or main biological pathways involved in those cardiovascular conditions." (PMID 30914768, 2019). "In recent years, interesting studies explored the role of IL-1 signal pathway in the progression of atherosclerosis due to its direct effect on the synthesis of different inflammatory cytokines, including IL-6 and CRP." (PMID 31110500, 2019). "Atherosclerosis is characterized by systemic inflammation, and high levels of C-reactive protein (CRP), a circulating predictor of inflammation, are found in patients, so it has been proposed as a biomarker of atherosclerosis." (PMID 31653058, 2019). "The inflammatory mediators, postulated as a major mechanism of RDW and atherosclerosis, including C-reactive protein, brain natriuretic peptide, erythropoietin, nitric oxide, fibrinogen, and cytokines, were not measured." (PMID 31324033, 2019). "Many kinds of modifications can occur to deposited LDL in arteries; however, two types of modified LDL prepared in vitro, oxidized LDL (ox-LDL) and enzymatically-modified LDL (E-LDL), are mostly used in experiments to define the role of CRP in atherosclerosis." (PMID 31379851, 2019). "Here, we review the literature on the structure-function relationships of CRP in vitro and in vivo as applied to atherosclerosis and conclude that CRP plays a defensive role in the pathogenesis of atherosclerosis." (PMID 31379851, 2019). "The combined data suggest that native CRP was either incapable or only partly capable for protecting against atherosclerosis in animal models." (PMID 31379851, 2019). "Other CpGs in the genes NOD2 and TCP11L1 have been linked to atherosclerosis, and in the TSNARE1 gene, with CRP." (PMID 31212707, 2019).
atherosclerosis (continued). "It induces atherosclerosis locally by inducing inflammation at a plaque site and systemically via the hepatic acute-phase reaction, which involves CRP, angiotensinogen, fibrinogen, and complement components." (PMID 31582904, 2019). "To date, CRP appears to be the only inflammatory marker used as a potential predictor of overall atherosclerosis." (PMID 29535705, 2018). "This was confirmed by the JUPITER trial, suggesting CRP as a marker of inflammation and atherosclerosis." (PMID 29867478, 2018). "The detection of inflammatory biomarkers such as CRP and adhesion molecules IL-6 and MMPs can be a good means of diagnosing atherosclerosis and cardiovascular disease." (PMID 30142970, 2018). "A plausible link between LpPLA2 activity and CRP activation is supported by the detection of CRP/ox-LDL complexes in the plasma of atherosclerosis patients." (PMID 29892284, 2018). "C-reactive protein (CRP), the most widely known inflammatory factor, is associated with vascular stiffness, BP, and atherosclerosis." (PMID 30087862, 2018). "And therefore CRP is a proinflammatory factor related to the occurrence and development of atherosclerosis." (PMID 29739462, 2018). "Pro-inflammatory cytokines, such as IL-1, TNF-α, C-reactive protein (CRP), IL-2, and IL-6, all increase in patients with atherosclerosis." (PMID 30386532, 2018). "Increased levels of CRP strongly predict the thrombotic complications of atherosclerosis, principally myocardial infarction and its adverse outcomes such as left ventri-cular failure, cardiac death, and ventricle rupture." (PMID 29552019, 2018). "Acute phase response, mediated by pro-inflammatory cytokines like CRP, IL-6 and IL-8, in its chronic state, leads to chronic disorders including atherosclerosis and cardiovascular events." (PMID 29439738, 2018). "C-reactive protein levels can often provide useful information for diagnosing, treating, and monitoring patients with atherosclerosis, and confirm patient responses to various stimulant factors." (PMID 30142970, 2018). "The ability of CRP to bind and interact with multiple ligands underscores its implication in different steps of atherosclerosis and CVD." (PMID 29552019, 2018). "High‐sensitivity C‐reactive protein (hs‐CRP) and lipoprotein‐associated phospholipase A2 (Lp‐PLA2) have been reported to be independent predictors of atherosclerosis." (PMID 30094934, 2018). "C-reactive protein contributes significantly to atherosclerosis owing to its predictive influence for cardiovascular events." (PMID 30524759, 2018). "CRP contributes to atherosclerosis progression by exerting pro-inflammatory effects, modulating the innate immune response and activating the complement system, promoting platelet activation, thrombus formation, vascular remodeling, and angiogenesis." (PMID 29552019, 2018). "In the setting of atherosclerosis, CRP upregulates VEGF expression via activating hypoxia inducible factor-1α, and MMP-2 expression and in adipose-derived stem cells, significantly increasing endothelial cell tube formation and vasa vasorum proliferation." (PMID 29552019, 2018). "In the Multi-ethnic Study of Atherosclerosis (MESA) study, continuous strong, positive associations between GGT and CRP, interleukin-6 (IL-6), and soluble intercellular adhesion molecule-1 (sICAM-1) were observed in multivariable models." (PMID 29491346, 2018). "In a study of subclinical atherosclerosis, plasma miR-21a levels were positively correlated with systolic, diastolic blood pressure, CRP and cIMT, but negatively correlated with nitric oxide (NO) and eNOS." (PMID 30347712, 2018). "Other cytokines, among them IL-10 and IL-6, are released in the process of atherosclerosis development, and C-reactive protein (CRP) synthesis is increased by the liver." (PMID 29453342, 2018). "Interleukin 6 is the most potent driver of CRP production in response to infection, trauma, and atherosclerosis." (PMID 30647800, 2018).
atherosclerosis (continued). "Oxidative stress is often linked to inflammation; HCY is as well a proinflammatory factor that is able to stimulate C-reactive protein production in vascular smooth muscle cells, accelerating the pathogenesis of atherosclerosis." (PMID 29098089, 2017). "It is well known that inflammation plays a crucial role across all stages of atherosclerosis including plaque progression, rupture, and thrombotic complications, and CRP is deposited in the arterial intima at the sites of atherogenesis." (PMID 29376057, 2017). "C-reactive protein, haemoglobin concentration and triglycerides were significantly lower in the healthy individuals as compared to atherosclerosis patients." (PMID 28698603, 2017). "CRP directly influences several phases of atherosclerosis via complement activation, apoptosis, vascular cell activation, monocyte recruitment, lipid accumulation, and thrombosis." (PMID 29158612, 2017). "Andrographolide (10 and 20 mg/kg, p.o. over 12 weeks) in P. gingivalis-induced atherosclerosis male white New Zealand rabbits (n = 6) reduced in IL-1β and -6, and CRP." (PMID 28878680, 2017). "Further, inflammatory markers such as white blood cell count (WBCC) and C-reactive protein (CRP) can predict CVD, and have been associated with atherosclerosis." (PMID 28376102, 2017). "CRP as a marker of inflammatory processes is known to play a central role in the pathogenesis of atherosclerosis and its elevated plasma levels have been found to predict future cardiovascular risk." (PMID 28528429, 2017). "The role of CRP as an independent predictor of the extent of atherosclerosis is debated, where some studies support this, while other studies do not." (PMID 28376102, 2017). "In this study, we assessed the impact of CLA supplementation on the levels of atherosclerosis markers – high-sensitivity C-reactive protein (hs-CRP) and asymmetrical dimethylarginine (ADMA)." (PMID 27834186, 2016). "β2GPI/CRP, oxLDL/β2GPI, and LP(a)/β2GPI complexes in serum can accelerate progress of atherosclerosis." (PMID 27818568, 2016). "Inflammation is considered to play a key role in the atherosclerosis process and CRP is currently the most validated inflammatory biomarker." (PMID 27658041, 2016). "Inflammation is the nature in atherosclerosis, and CRP is an inflammation marker in the prediction of cardiovascular events." (PMID 27164124, 2016). "Our data revealed a significant association of CRP and SAA1 variants with both CRP and SAA levels, which are highly correlated with multiple atherosclerosis-related traits." (PMID 27313400, 2016). "Elevation of circulating CRP has been recognized as a predictive marker for atherosclerosis and cardiovascular diseases." (PMID 27460564, 2016). "The possible mechanistic role of CRP in plaque deposition is highly complex, exerting proatherogenic effects in many cells involved in atherosclerosis." (PMID 28190984, 2016). "Transgenic over expression of CRP in mice and in vivo injection of large doses of human CRP have minimal effect on inflammation and atherosclerosis." (PMID 28190984, 2016). "Increased CRP promotes inflammation and atherosclerosis via increase in expression of plasminogen activator inhibitor-1 and adhesion molecules in endothelial cells and leading to an increase in LDL uptake into macrophages." (PMID 27310963, 2016). "The increased serum levels of MRP8/14 and CRP in CAD aggravate the development of atherosclerosis and mediate the rupture of instable plaque." (PMID 27022611, 2016). "CRP, a phylogenetically highly conserved plasma protein, is the classical acute phase reactant in humans, and preliminary evidence for interaction of CRP with lipids implicates a possible relationship between CRP and atherosclerosis." (PMID 27553960, 2016). "Interleukin (IL)-6, one of the most potent drivers of CRP production, is released from activated leukocytes in response to infection or trauma and from vascular smooth muscle cells in response to atherosclerosis." (PMID 28190984, 2016).
atherosclerosis (continued). "Second, the understanding of the role of CRP isoforms and their interactions with oxidized lipids in atherosclerosis and other cardiovascular diseases should be expanded." (PMID 27738646, 2016). "The relationship between the CRP and the total homocysteine (Hcy), folate, and vitamin B12 levels is revealed as an early marker of the generalized atherosclerosis." (PMID 25904961, 2015). "The surrogate markers of atherosclerosis assessed were carotid intima-media thickness (cIMT), C-reactive protein (CRP) and Young’s modulus, measures of arterial wall thickness, inflammation and arterial stiffness, respectively." (PMID 26408307, 2015). "Systemic increases in these inflammatory molecules, together with tumor necrosis factor and CRP, occur during the atherosclerosis process." (PMID 25433580, 2015). "CRP and sP-selectin showed significant changes reflecting effects on inflammation and atherosclerosis in those given selenium and coenzyme Q10 combined." (PMID 26375288, 2015). "Inflammation plays a critical role in the risk for and progression of CVD such that inflammatory biomarkers like CRP and IL-6 are generally recognized as independent predictors of atherosclerosis." (PMID 26080804, 2015). "Some of these cytokines enter circulation and stimulate production of C-reactive protein (CRP) in the liver that is known as a predictor of atherosclerosis." (PMID 26157708, 2015). "Because inflammation contributes to atherosclerosis generation, inflammatory biomarkers such as CRP and MPO are usually used to diagnose and assess the prognosis of coronary artery disease." (PMID 26405438, 2015). "It is known that CRP participates in initiation and progression of atherosclerosis through modulating the activities and expressions of multiple factors implicated in atherogenesis." (PMID 26131983, 2015). "An increasing number of studies have suggested there are close relationships between CRP and atherosclerosis as well as cerebral infarction." (PMID 26609318, 2015). "CRP is not only a significant prognosticator of future cardiovascular events but also it is a direct participant in the pathogenesis of athero-sclerosis." (PMID 25864817, 2015). "Pentameric CRP was suggested to upregulate the activation of DNA binding protein complex NF-κB, a key mediator of atherosclerosis and the expression of monocyte chemoattractant protein-1 (MCP-1) in human endothelial cells." (PMID 26089599, 2015). "We cannot rule out the influence of cumulative disease activity measured by DAS28 and CRP in the development of subclinical atherosclerosis given the cross-sectional nature of our study." (PMID 25821796, 2015). "Overall, these findings confirm the idea of CRP dissociation as a promising target to prevent proinflammatory amplification in acute (cardiac ischemia/reperfusion) and chronic (atherosclerosis) diseases." (PMID 26089599, 2015). "C-reactive protein has been taken as an inflammatory marker since it usually has significant increase under such conditions like severe bacterial infections, atherosclerosis, vascular injury, ischemia, and necrosis." (PMID 26609318, 2015). "In RA, the average CRP correlates with the presence of subclinical atherosclerosis measured by carotid intima-media thickness (IMT)." (PMID 25890227, 2015). "On the other hand, many controversial and contradictory results from both human and experimental animals have been published on the effects of CRP on atherosclerosis." (PMID 24872601, 2014). "There are many problems of using mouse models for the study of CRP's physiological functions and controversies have risen in regard to CRP's roles in atherosclerosis." (PMID 24872599, 2014). "QSYQ can reduce high sensitivity C reactive protein level in atherosclerotic rabbit to prevent the progress of atherosclerosis by inhibiting inflammatory reaction." (PMID 24817581, 2014). "If CRP is proinflammatory and atherogenic, can we target CRP for the prevention and treatment of atherosclerosis ?" (PMID 24872599, 2014).
atherosclerosis (continued). "This is in agreement with the findings that in atherosclerosis, an inflammatory disease characterized by elevated levels of CRP and IL-6, a low vagal tone is inversely correlated with these inflammatory markers." (PMID 25207649, 2014). "CRP has also been shown to bind to ox-LDL in vivo in diabetes mellitus patients with atherosclerosis and when ox-LDL is complexed with β2 glycoprotein I." (PMID 24948846, 2014). "This review presents the molecular basis and currently known mechanisms for the involvement of CRP in development and progression of atherosclerosis." (PMID 27433484, 2014). "It is assumed that CRP is involved in modulation of developing atherosclerosis, because CRP and ox-LDL are present in atherosclerotic lesions." (PMID 24741613, 2014). "Levels of anti-EPC antibodies were determined in 100 subjects and differential risk score for atherosclerosis, as well as to circulating EPC levels and the inflammatory markers IL-6 and C-reactive protein." (PMID 24945945, 2014). "Beside all those epidemiological and genetic studies, the experimental investigations also try to reveal the role of CRP in the progress of atherosclerosis." (PMID 24808639, 2014). "C-reactive protein (CRP) is synthesized in the liver and is a peripheral marker of systemic inflammation but is also associated with atherosclerosis and cardiovascular diseases (including coronary insufficiency)." (PMID 24497930, 2014). "As primary proinflammatory cytokines, IL-6 and CRP are sensitive measures of the burden of systemic atherosclerosis and extent of atherosclerotic activity." (PMID 24708887, 2014). "In our previous study, we found that WHHL rabbits are an excellent model for the study of CRP and its relationship with atherosclerosis because they have higher levels of plasma CRP and immunoreactive CRP proteins are present in lesions of atherosclerosis." (PMID 24872601, 2014). "In conclusion, according to our current study, Hs-CRP/APN ratio was a useful predictor for atherosclerosis progression and clinical events." (PMID 25070472, 2014). "The significance of CRP as a predictor of atherosclerosis-related events, however, remains controversial." (PMID 25490200, 2014). "A decade ago, we used both cholesterol-fed rabbits and WHHL rabbits and revealed several important features of CRP and their relationship with atherosclerosis." (PMID 24872599, 2014). "Simultaneously, CRP favors the establishment of a generalized chronic inflammatory state and in turn potentiating atherosclerosis." (PMID 27433484, 2014). "Possible mechanisms include a role for CRP as an inflammatory marker and the formation of atherosclerosis, and its role in the vascular diseases." (PMID 24755778, 2014). "After a decade's effort using these unique models, it is time to draw a conclusion regarding the true role of CRP in atherosclerosis." (PMID 24872599, 2014). "Studies demonstrated that increased serum levels of C-reactive protein (CRP), interleukin (IL)-6, tumor necrosis factor (TNF)-α, and pentraxin (PTX)-3 are important risk factors for atherosclerosis, and cardiovascular diseases." (PMID 24481114, 2014). "If CRP as a proatherogenic factor was documented, therapeutic approaches aimed at inhibiting CRP's effects in patients with atherosclerosis would obviously be of interest." (PMID 24872599, 2014). "As such, a previous study confirmed an association between PTX3, CRP, LDL cholesterol and coronary artery disease severity in patients with intermediate-high atherosclerosis severity." (PMID 25014007, 2014). "Previous studies suggested that higher RDW was associated with inflammatory markers such as soluble tumor necrosis factor receptors and CRP in the setting of atherosclerosis and other chronic diseases." (PMID 24606910, 2014). "A recognized biological marker, high-sensitivity C-reactive protein, has been used widely to assess the progression of atherosclerosis and inflammation." (PMID 24282409, 2013).